HSP90AA1 (heat shock protein 90 alpha family class A member 1)
Diseases named in the same sentence as HSP90AA1 in open-access papers (continued):
Sharing a sentence is not in itself a finding about the gene and the disease.
liver cancer (14 papers, 2019 to 2025). An epithelial or non-epithelial malignant neoplasm that arises from the liver. "We found that HSP90AA1 played a key role in the human gene network associated with liver cancer, and HSP90A (encoded by HSP90AA1) was more likely to bind (20S) G-Rh2." (PMID 34884975, 2021). "Heat shock protein 90α (HSP90AA1) in the core target is often highly expressed in liver cancer and is associated with adverse prognosis, and its strong binding to cinnamic acid (−5.7 kcal/mol) may provide new ways to overcome a drug resistant target." (PMID 40872596, 2025). "The relationship between RA and HSP90AA1, a protein essential for the survival and growth of cancer cells in liver cancer, was examined using molecular docking and dynamics simulations." (PMID 40427522, 2025). "This suggests that RA acts similarly to how it inhibits HSP90AA1 in liver cancer." (PMID 40427522, 2025). "Animal models play a crucial role in understanding the role of HSP90AA1 in liver cancer." (PMID 38785796, 2024). "While many genes get high EGIS in specific cancer types, such as HSP90AA1 in pancreatic cancer, AKT1 in glioblastoma and pancreatic cancer, and ACTB in glioblastoma and liver cancer." (PMID 40478912, 2025). "The results revealed that the expression of HSP90AA1, PPIA, SQSTM1, and USP21 was significantly increased in liver cancer tissues compared with normal liver tissues (p < 0.05), which was consistent with the results of the bioinformatics analysis." (PMID 36795724, 2023). "In summary, seven of the genes (VEGFA, CTNNB1, SPP1, PPARG, RAC1, HSP90AA1, and LGALS3) were highly unregulated in patients with liver cancer." (PMID 35069936, 2022). "Genes with 5-mC and 5-hmC level changes enriched in these pathways, such as BMP4, HSP90AA1, DAPK3, FADD and CASP8, have been already reported as potential epigenetic biomarkers for liver cancer." (PMID 31337442, 2019). "To support our hypothesis, we analyzed the survival probability of multiple types of cancer patients in the TCGA database, showing that lower HSP90AA1 expression predicted better survival and prognosis in ESCC, EAC, head-neck squamous cell carcinoma, and liver cancer." (PMID 34294701, 2021).
gastric cancer (13 papers, 2018 to 2025). A primary or metastatic malignant neoplasm involving the stomach. "On the other hand, Heat Shock Protein 90 Alpha Family Class A (HSP90AA1) was also identified from the RNA sequencing data as a crucial component in the pathways associated with gastric cancer." (PMID 40141751, 2025). "A clinical study with 206 gastric cancer patients reported that loss of HSP90AA1 is associated with positive clinical outcomes." (PMID 30153855, 2018). "The overexpression of HSP90AA1 is associated with multiple cancer types, including gastric cancer." (PMID 40141751, 2025). "Moreover, high expression of HSP90AA1 is associated with disease progression and poor survival in patients with gastric cancer." (PMID 34226297, 2021). "None of the promoter methylation expression levels of CA2, NR3C1, and HSP90AA1 were significantly different in gastric cancer." (PMID 40995432, 2025). "The target proteins implicated in gastric cancer, specifically HIF1A, HSP90AA1, MMP9, ERBB2, and PTGS2, were matched with the key metabolites from the Vaccinium genus, including cyanidin 3-O-glucoside, ursolic acid, resveratrol, scopoletin, and (+)-catechin." (PMID 40141751, 2025). "The RNA sequencing data highlight several key proteins—HIF1A, HSP90AA1, PTGS2, MMP9, and ERBB2—which are associated with various stages of gastric cancer progression and align with established biomarkers and pathways." (PMID 40141751, 2025). "HSP90AA1 also plays a downstream regulatory role in the proliferation and metastasis of gastric cancer." (PMID 36765042, 2023). "In conclusion, ZNRD1-AS1 levels were upregulated in gastric cancer tissues, and knockdown of ZNRD1-AS1 suppressed gastric cancer cell proliferation and metastasis by targeting the miR-9-5p/HSP90AA1 axis." (PMID 34226297, 2021). "Therefore, targeting HSP90AA1 with specific inhibitors in gastric cancer treatment represents a promising therapeutic approach." (PMID 40141751, 2025). "Similarly, HSP90AA1 is highly expressed in both primary and early gastric cancer stages, consistent with its role in advanced tumor stages and stress resistance." (PMID 40141751, 2025). "HSP90AA1, as the target of miR-9-5p, could be targeted to suppress gastric cancer cell proliferation and metastasis, and the MAPK1/3 pathway has played crucial roles in H. pylori infection, CG, and gastric cancer." (PMID 36299773, 2022). "We hypothesized that ZNRD1-AS1 might be involved in the pathogenesis of gastric cancer by functioning as a ceRNA of miR-9-5p to regulate heat shock protein 90 alpha family class A member 1 (HSP90AA1)." (PMID 34226297, 2021). "Analysis by the GEPIA database revealed (tumor = 408, normal = 211) that CA2 and HSP90AA1 were differentially expressed in gastric cancer, CA2 (p < 0.05) was lowly expressed in gastric cancer, and HSP90AA1 (p < 0.05) was highly expressed in gastric cancer." (PMID 40995432, 2025). "In this experiment, WGCNA and machine learning algorithms were used to predict CA2, HSP90AA1, and NR3C1, the core targets of white Atractylodes against gastric cancer." (PMID 40995432, 2025).
glioblastoma (12 papers, 2017 to 2025). The most malignant astrocytic tumor (WHO grade IV). "Based on the key module, HSP90AA1 and AKT1 were selected as the key genes of sciadopitysin targets in glioblastoma." (PMID 38911393, 2024). "They did however find higher expression of HSP90AA1 and HSP90AB1 in the recurrent glioblastomas." (PMID 36358853, 2022).
melanoma (12 papers, 2017 to 2025). A malignant, usually aggressive tumor composed of atypical, neoplastic melanocytes. "The inhibition of secreted HSP90AA1 with chemical inhibitors, such as 17-allylamino-17 demethoxygeldanamycin (17AAG) and monoclonal antibody against HSP90AA1 (mAb 4C5), thus reduced in vitro invasion and metastasis in mouse melanoma models." (PMID 28468249, 2017). "Accordingly, secreted HSP90AA1 promoted breast cancer and melanoma invasion in vitro and increased metastatic potential in animal models." (PMID 28468249, 2017). "It upregulates DAMPs (HMGB1, HSPA4, and HSP90AA1) in melanoma cells, for example." (PMID 39759512, 2024). "In addition, the presence of serum HSP90AA1 was positively correlated with tumor malignancy in patients presenting cancer of the liver, breast, lung, pancreas or melanoma." (PMID 28468249, 2017). "A core group of differentially expressed genes (FTH1, FTL, HSPA8, HSP90AA1, and HSP90B1) was recurrently identified within significantly enriched pathways across TCGA melanoma samples and clinical cohorts." (PMID 32296058, 2020).
ovarian carcinoma (12 papers, 2019 to 2024). A malignant neoplasm originating from the surface ovarian epithelium. "A high expression of HSP90AA1 can increase the chemical resistance of ovarian cancer SKOV3 cells to cisplatin and reduce the apoptosis induced by cisplatin." (PMID 35263200, 2022). "HSP90AA1 RNAi could inhibit the proliferation of ovarian cancer SKOV3 cells and increase its apoptosis." (PMID 35411258, 2022). "HSP90AA1 is considered as a potential protein target in therapy of ovarian cancer." (PMID 32293263, 2020). "In addition, the PI3K-Akt signaling pathway might be the main pathway for SMB to inhibit ovarian cancer because the significant genes HSP90AA1, CDK2, and PIK3CG in this pathway receive the action of multiple ingredients in SMB." (PMID 36483919, 2022). "Kaplan–Meier curve analysis revealed a significant correlation (p < 0.05) between low expression of HSP90AA1, HSPA8, PSMA5, and SOD1 and prolonged overall survival (OS) in ovarian cancer patients." (PMID 38166541, 2024). "HSP90AA1 and CDK2 were selected by the analysis of the relationship between SMB and ovarian cancer, and the relationship between the PI3K-Akt signaling pathway and SMB." (PMID 36483919, 2022). "Abnormal expression of HSP90AA1 and CDK2 could affect the progression of ovarian cancer." (PMID 36483919, 2022). "HSP90AA1, CDK2, and PIK3CG might be potential targets of SMB in inhibiting ovarian cancer." (PMID 36483919, 2022).
colorectal cancer (11 papers, 2017 to 2025). A primary or metastatic malignant neoplasm that affects the colon or rectum. "In colorectal cancer, there is a positive correlation between high expression of HSP90AA1 and poorer prognosis of patients." (PMID 36874006, 2023). "Then, a series of in vitro and in vivo experiments were conducted to reveal the role of DAB2IP and HSP90AA1 in the invasion and metastasis of colorectal cancer, and flow cytometry was used to explore their effects on apoptosis." (PMID 35590292, 2022). "Studies have shown that the expression of HSP90AA1 in colorectal cancer precancerous lesions depends on the malignant potential of the polyps." (PMID 35899228, 2022). "Earlier studies showed that KCNQ1OT1 promoted NSCLC progression by modulating miRNA-27b-3p/HSP90AA1 axis, and stimulated cholangiocarcinoma development via miR-140-5p/SOX4 axis, and facilitated the migration and EMT of colorectal cancer by forming a feedback loop with miR-217 and ZEB1." (PMID 32821247, 2020). "DAB2IP also acts as a negative modulator of HSP90AA1 in colorectal cancer; through an unknown mechanism, DAB2IP inhibits HSP90AA1-mediated upregulation of SRP9, fostering activation of the pro-apoptotic JNK/ASK1 pathway and counteracting metastasis." (PMID 38902547, 2024). "However, the specific regulatory mechanism of DAB2IP and HSP90AA1 in colorectal cancer (CRC) is not clear." (PMID 35590292, 2022).
diabetes (11 papers, 2017 to 2025). "In diabetes, HSP90AA1 is implicated in managing cellular stress responses, particularly within the AGE-RAGE pathway, which drives chronic inflammation." (PMID 40800999, 2025). "Pharmacological inhibition of HSP90AA1 in mice with diabetes or diet-induced obesity and IR improves insulin sensitivity through the activation of HSF1, a key regulator of stress response." (PMID 40004184, 2025). "HSP90AA1 was previously identified as a node in a protein-protein interaction network in diabetes through bioinformatics analysis." (PMID 38031191, 2023). "Changes in the expression of related HSPs (HSPA8, HSP90AA1, and HSPA5,) have been confirmed in complications of diabetes and are functionally related to hyperglycemia-induced cell damage." (PMID 32851081, 2020). "Notably, the PI3K-Akt signaling pathway, a critical pathway in diabetes, was enriched with additional key targets, including IL6, HSP90AA1, FN1, MAPK1, AKT1, PIK3R1, and MAPK3." (PMID 40170727, 2025). "In conclusion, these results suggest a significant increase in HSP90AA1 and HSPA8 concomitant with diabetes, and SREBF2 and GTAT2 may regulate the expression of HSP90AA1 and HSPA8." (PMID 38166541, 2024). "In addition, the cytoHubba plug-in has identified four key targets (HSP90AA1, AKT1, SRC, and MAPK1) that have a significant connection to the pathogenesis and treatment of type 2 diabetes mellitus." (PMID 38031191, 2023). "Through the PPI network screening, it was found that 5 key genes (YWHAZ, HNRNPA1, HSPA8, HSP90AA1, and HSPA5) obtained through protein interactions may provide new ideas for the treatment of diabetes." (PMID 32851081, 2020).
atherosclerosis (10 papers, 2022 to 2026). A disease characterized by the build-up of fatty material and calcium deposition in the arterial wall resulting in partial or complete occlusion of the arterial lumen. "Network pharmacology and molecular docking results revealed that several blood-brain barrier (BBB)-permeable active components of Lonicera caerulea, including Naringenin and Palmatine, may be associated with targets involved in the lipid and atherosclerosis pathway, such as HSP90AA1, SRC and TNF." (PMID 42196534, 2026). "In this study, EGFR, VEGFA, HSP90AA1, SRC, HIF1A, CXCR4 and IGF1R were identified as key hub targets, which linked anthocyanins with atherosclerosis." (PMID 40478326, 2025). "Additionally, HSP90AA1 is involved in the IL-17 signaling pathway, fluid shear stress and atherosclerosis, and NOD-like receptor signaling pathway, further emphasizing the interplay between these pathways." (PMID 41394816, 2025). "NBP can stably bind ALB, ESR1, EGFR, HSP90AA1, and other targets, and may play a role in neuroprotection for patients with DEACMP by modulating Lipid and atherosclerosis, IL-17 signaling pathway, MAPK signaling pathway, FoxO signaling pathway, PI3K/AKT signaling pathway." (PMID 37006490, 2023).
viral infection (10 papers, 2020 to 2025). "Across disease models, elevated HSP90AA1 expression has been correlated with cancer, neurodegeneration, inflammation and viral infection, although its relevance to human CKD remains understudied." (PMID 41334230, 2025). "The involvement of HSP90AA1, a highly-conserved molecular chaperone, in viral infections has since a long time been discussed to be involved in the infection of a range of viruses." (PMID 33585804, 2021). "Among them, HSP90AA1 belongs to the HSP90 family and is one of the most important molecular chaperones evolved to maintain functionally active of client proteins under both physiological and temperature stress conditions such as cancers, heat shock, and virus infection." (PMID 37099596, 2023). "We hypothesize that HSP90AA1 is not the main molecule for CSFV to escape innate immunity, there are still other key proteins that help CSFV to escape innate immunity, but HSP90AA1 is important for establishing an intracellular antiviral immune state, which helps to limit viral infection." (PMID 36405689, 2022).
colon carcinoma (9 papers, 2021 to 2025). "The PPI network, visualized through the STRING database, identified key targets such as AKT1, IL6, and HSP90AA1, which are implicated in colon cancer development." (PMID 41011246, 2025). "HSP90AA1 is tightly related to gastrointestinal cancers, such as esophageal, gastric, and colon cancers, and can be predictive biomarkers for these cancers." (PMID 33743701, 2021). "We investigated the differences in the expression of DAB2IP, HSP90AA1 and SRP9 among different subtypes of CMS classification in colon cancer." (PMID 35590292, 2022). "On the other hand, the expression of Hsp90aa1 and Hsp90ab1 increased in colon cancer cells, regardless of the cancer grade, compared to that in normal colon fibroblast cells (CCD18Co)." (PMID 34620942, 2021).
systemic lupus erythematosus (9 papers, 2013 to 2025). An autoimmune multi-organ disease typically associated with vasculopathy and autoantibody production. "Three HSP90AA1 polymorphisms (rs7160651, rs10873531 and rs2298877) were associated with the response of systemic lupus erythematosus patients to glucocorticoids treatment, thus indicating that an HSP90AA1 variation may affect GR function." (PMID 41010037, 2025). "The aim of the present study was to explore whether single nucleotide polymorphisms (SNPs) within HSP90AA1 gene affect the response of systemic lupus erythematosus (SLE) patients to GCs treatment." (PMID 27026916, 2016). "To elucidate the alterations in glucose metabolism and HSP90AA1/PI3K/AKT signaling pathway activity in lupus prone mice with hUC‐MSCs treatment, we analyzed the levels of glucose metabolites and relevant signaling components." (PMID 40801323, 2025). "HSP90AA1 affects the patient’s reaction with systemic lupus erythematosus to glucocorticoids and the lipopolysaccharide-induced inflammatory response, including tumor necrosis factor secretion by monocytes, according to previously published findings." (PMID 35330393, 2022). "Inhibition of HSP90AA1 exhibited a decrease protein expressions of glucose enzymes, HSP90AA1, PI3K, and p‐AKT in splenic CD4+ T cell of lupus‐prone mice." (PMID 40801323, 2025). "Inhibition of HSP90AA1 exhibited a decrease mRNA levels of glucose enzymes, Hsp90aa1, Pi3k, and Akt in splenic CD4+ T cell of lupus‐prone mice." (PMID 40801323, 2025). "In 2D electrophoresis, the visible DNA-bound protein complex in EMSA was excised from a native PAGE gel and sequenced directly, which identified lupus autoantigen Ku70/80 (XRCC5/6), nucleolin (NCL) and HSP90AA1/AB1 as the major constituents of the DNA–protein band." (PMID 23441136, 2013). "ESR1, TNF, SRC, HSP90AA1, and CASP3 further contribute to immunoregulation via distinct mechanisms: ESR1 influences the activity of T and B cells and plays a role in the treatment of sex-related autoimmune diseases, such as rheumatoid arthritis and systemic lupus erythematosus." (PMID 39717552, 2024).
depression (8 papers, 2022 to 2025). "It is possible that the HSP90AA1 polymorphisms may be associated with the severity of depression and anxiety symptoms in SCZ." (PMID 41010037, 2025). "Higher HSP90AA1 expression is linked to depression in HCC patients." (PMID 38785796, 2024). "It was verified that HSP90AA1 was up-regulated in patients with depression, which correlated with elevated levels of VEGF, VEGFR2, PI3K, and AKT1." (PMID 36045654, 2022). "Among these core targets, SIRT1, HIF1A, ESR1, VEGFA, HSP90AA1 and PTGS2 are well documented to be associated with depression." (PMID 36496991, 2022).
Alzheimer disease (7 papers, 2017 to 2025). A progressive, neurodegenerative disease characterized by loss of function and death of nerve cells in several areas of the brain leading to loss of cognitive function such as memory and language. "It was noteworthy that the expression levels of RELA and HSP90AA1 were enriched in Alzheimer’s disease pathways, suggesting their potential important roles in the AD process." (PMID 36159817, 2022). "The pathways impacted by HSP90AA1 were mainly enriched in the activation of extracellular related biological processes, including cell response to DNA damage stimulus, response to heat, Alzheimer’s disease, and protein folding." (PMID 37259027, 2023). "The overexpression of HSP90AA1 has been observed in Alzheimer’s disease, and the use of inhibitors, geldanamycin and its analogs, has been proposed as a potential therapeutic strategy due to its role in tau stabilization and amyloid-beta aggregation, a hallmark feature of this disease." (PMID 38002524, 2023).